IL1A (interleukin 1 alpha)
Diseases named in the same sentence as IL1A in open-access papers (continued):
Sharing a sentence is not in itself a finding about the gene and the disease.
Obesity (continued). "IL-1α is one of the proinflammatory cytokines; however, it has not been clarified whether IL-1α may also cause obesity." (PMID 22216303, 2011). "IL-1α may have a critical function in the development of obesity." (PMID 22216303, 2011). "Our findings imply IL-1α may have a critical function in the development of obesity in humans." (PMID 22216303, 2011). "The intervention with OliveOil+DietBra effectively decreased the levels of fasting insulin, IL-1α and adiponectin, suggesting its beneficial role in improving the inflammatory profiles and fasting insulin levels in adults with class II/III obesity and T2DM." (PMID 35586621, 2022). "Olive oil combined with DietBra decreased fasting insulin, IL-1α and adiponectin, while inducing a reduction in BMI and weight in individuals with T2DM and class II/III obesity." (PMID 35586621, 2022). "In serum and synovial fluid, eight obesity-induced inflammatory cytokines (VEGF, MIP-1α, MIP-2, IP-10, IL-1α, TNF-α, MCP-1, and leptin) and LPS were increased in the DIO-KOA group compared with the control group." (PMID 32724821, 2020). "Obesity-induced inflammation tends to exacerbate metabolic disorders, and we also found improvements in inflammatory markers, manifested as the decrease of inflammatory factors TNF-α, IL-1α, IL-6, and chemokine Eotaxin elicited by nicotine." (PMID 41488304, 2025). "Moreover, adipose tissue in older adults with obesity functions as a dynamic endocrine organ, secreting an array of hormones and pro-inflammatory cytokines, like TNF-a, IL-1a, IL-6, and CRP." (PMID 38668557, 2024). "Cytokine analysis revealed significantly increased IL-1α and IL-17Α in white adipose tissue from young SSPN−/− male mice, which may be protective from diet-induced obesity." (PMID 39120469, 2024). "There is increasing evidence that the induction of inflammation and production of inflammatory mediators released from the adipose tissue of obese subjects, such as adipocytokines and classical cytokines contribute to obesity-induced NAFLD, in which IL-1α/β plays a key role." (PMID 31507607, 2019). "We observed that IL-1α, but not IL-1β serum levels were significantly influenced by EDs diagnosis, being essentially higher in AN patients or patients with obesity with or without BED than in HCs, while they were not influenced by BMI or depression." (PMID 31450770, 2019). "The role of IL-1α in obesity has not been studied yet, and there are no studies that examine the effect of IL-1α in both in vivo and in vitro." (PMID 22216303, 2011). "Consistent with our hypothesis, certain inflammatory markers, as IL-2, IL-10, IFN-γ and IL1-α, were found to differ between AN and HCs, as well as between AN and participants with obesity with or without BED." (PMID 31450770, 2019). "Although in our studies we cannot discount IL-1α involvement, we hypothesize that it does not play a role in obesity-induced hepatic steatosis development." (PMID 25216251, 2014). "There have been no reports on the effects of obesity on the adipose tissue content of IL-1α." (PMID 22216303, 2011). "IL-18 (R2:0.355, P < .01) and IL-1ra (R2:0.287, P < .05) correlated with BMI, whereas IL-1α did not.Conclusions.Accumulating data indicate the importance of the endocrine function of adipose tissue for the pathophysiological consequences of obesity-related co-morbidities." (PMID 20169140, 2010). "Therefore, this evidence suggests that a high DII intake can lead to obesity in women, and the increase in abdominal adipose tissue may alter serum IL-1α concentrations irrespective of the presence or absence of a healthy metabolic profile." (PMID 36311488, 2022). "Altogether, for the first time, IL-1α, IL-10, EGF, and IFN-γ were shown to differ between AN and HCs, and between AN and individuals with obesity with or without BED." (PMID 31450770, 2019).
Obesity (continued). "Although the role of IL-1α in obese and GDM pregnancies has not been well characterised, there is growing evidence to implicate IL-1α to have a role in diabetes and obesity." (PMID 25849717, 2015). "IL-1ra and IL-18 correlated with all anthropometrical measurements of obesity, including body weight, BMI, BMI-SDS, and waist circumference, whereas IL-1α did not." (PMID 20169140, 2010).
rheumatoid arthritis (49 papers, 2005 to 2025). A chronic, systemic autoimmune disorder characterized by inflammation in the synovial membranes and articular surfaces. "Several meta-analyses have reported an association between IL1A rs17561, rs1800587 polymorphisms and the presence of various autoimmune diseases, including systemic lupus erythematosus, rheumatoid arthritis, multiple sclerosis and Graves’ disease." (PMID 29879187, 2018). "The rs17561 variant and the rs1800587 variant of IL1A gene are associated with erosive/aggressive arthritis and the rs1304037 variant of the IL1A gene is associated with rheumatoid arthritis." (PMID 28081267, 2017). "IL-1α has pleiotropic effects on a wide range of cell types, and it has been extensively studied for its ability to contribute to various autoimmune and inflammation-linked disorders, including rheumatoid arthritis, Alzheimer’s disease, systemic sclerosis and cardiovascular disorders." (PMID 22879895, 2012). "IL-1α-neutralizing antibodies are currently employed in the treatment of autoimmune diseases, such as rheumatoid arthritis, as they alleviate joint inflammation via modulation of IL-1α concentrations." (PMID 40940885, 2025). "Patients with systemic inflammatory disorders, such as rheumatoid arthritis, and a concurrent Zn shortage have been demonstrated to have higher levels of IL-1α, IL-1β, and IL-6 expression compared to those who consume more Zn." (PMID 37946846, 2023). "Recombinant IL-1Ra (generic anakinra) is fully active in blocking the IL-1 receptor 1 (IL-1R1), and thus the activities of IL-1α and IL-1β, and is approved for the treatment of rheumatoid arthritis and several other diseases." (PMID 35448559, 2022). "These genes are involved in immune system regulation, some of which are associated with the host response to rheumatoid arthritis (CCL20, IL1A, and MMP1)." (PMID 33301474, 2020). "IL-1Ra prevents the inflammation driven by either IL-1α and IL-1β, and is approved to treat rheumatoid arthritis for subcutaneous (s.c.)administration of 100 mg daily, but is widely used off-label." (PMID 32699149, 2020). "In brief, IL-1α is expressed locally, whereas IL-1β is expressed at the systemic level and in inflamed sites as synovial fluids in rheumatoid arthritis or gouty arthritis." (PMID 28197099, 2017). "A first step would be to use anakinra, a specific inhibitor of both IL-1α and IL-1β already clinically applied for the treatment of rheumatoid arthritis in humans." (PMID 25756043, 2015). "Among the cytokines, two forms of Interleukin-1 (IL-1α and IL-1β) are thought to play an important role in inflammation and involved in many pathological conditions including rheumatoid arthritis." (PMID 24705413, 2014). "IL-ra, a specific inhibitor of both IL-1α and IL-β generically known as anakinra is clinically applied for the treatment of rheumatoid arthritis." (PMID 24926998, 2014). "Serum levels of proinflammatory cytokines including TNF-α, IFN-γ, and IL-1α are increased in patients with rheumatoid arthritis and other autoimmune inflammatory disorders." (PMID 23217187, 2012). "Genetic variations in IL1RN, IL1A and IL1B have been associated with ulcerative colitis, gastric cancer and rheumatoid arthritis." (PMID 22322675, 2012). "Enrichment analysis with the DEGs demonstrated overrepresentation of KEGG (Kyoto Encyclopedia of Genes and Genomes) pathways for autoimmune diseases such as ‘rheumatoid arthritis’ and ‘inflammatory bowel disease’, which supported the proinflammatory nature of the IL1A-expressing TH17 cell subset." (PMID 36604548, 2023). "Additionally, canakinumab, a human monoclonal IL-1β antibody, and rilonacept, a decoy receptor of IL-1α and IL-1β, have been targeted in rheumatoid arthritis." (PMID 36387275, 2022). "Additionally, a human monoclonal IL-1β antibody canakinumab, and a decoy receptor of IL-1α and IL-1β rilonacept have been focused on in rheumatoid arthritis." (PMID 35833125, 2022).
rheumatoid arthritis (continued). "No positive association between IL1A rs1800587 and rs17561 SNPs and the risk of rheumatoid arthritis was observed." (PMID 29879187, 2018). "Our pooled data with enhanced statistical power also indicated that the IL1A rs1800587 and rs17561 SNPs were not linked to the risk of rheumatoid arthritis, which was consistent with previous data." (PMID 29879187, 2018). "Anakinra (brand name Kineret) is a recombinant version of IL-1Ra that is clinically used to treat rheumatoid arthritis, but may have a broader clinical impact in treating solid tumors that have increased IL-1α expression." (PMID 29502208, 2018). "Both IL-1α and IL-1β bind to the IL-1 type 1 receptor (IL-1R1), inducing a wide range of secondary inflammatory mediators and playing critical roles in regulating immune and inflammatory processes, such as rheumatoid arthritis (RA) and systemic lupus erythematosus." (PMID 40371323, 2025). "The aim of this study was to determine whether HMGB1 in complex with LPS, interleukin (IL)-1α or IL-1β has enhancing effects on the production of proinflammatory mediators by rheumatoid arthritis synovial fibroblasts (RASF) and osteoarthritis synovial fibroblasts (OASF)." (PMID 21871094, 2011). "Fortunately, some neutralizing antibodies against IL-1α and TNF-α are already in practical use for treating cancers, rheumatoid arthritis, and other chronic local inflammatory diseases." (PMID 38383466, 2024). "Anakinra, recombinant human IL-1 receptor antagonist, that blocks IL-1α and IL-1β, has been FDA approved for the treatment of rheumatoid arthritis since 2001." (PMID 34749739, 2021). "There are numerous studies on inflammatory cytokines such as IL-1α, IL-1β, and TNF-α in joint disorders, including osteoarthritis, rheumatoid arthritis, posttraumatic osteoarthritis, and hemophilic arthropathy." (PMID 33213419, 2020). "Low magnesium promotes inflammation and up-regulates IL1α and IL6 production in endothelial cells while magnesium supplementation attenuated the development of OA and rheumatoid arthritis (RA)." (PMID 29115971, 2017). "Synovial fibroblasts obtained from rheumatoid arthritis (RA) and osteoarthritis (OA) patients were stimulated with HMGB1 alone or in complex with LPS, IL-1α or IL-1β." (PMID 21871094, 2011). "However, IL1A rs17561 or rs1800587 polymorphism seems not to be statistically linked to the risk of other analyzed autoimmune diseases, such as systemic sclerosis, juvenile idiopathic arthritis, rheumatoid arthritis, multiple sclerosis and systemic lupus erythematosus." (PMID 29879187, 2018). "Recently, we reported that tumour necrosis factor (TNF)-α, IL-1α, IL-1β and IL-17 enhance Cyp7b mRNA expression and induce a concomitant increase in the formation of 7α-OH-DHEA by fibroblast-like synoviocytes (FLS) from rheumatoid arthritis patients." (PMID 16277680, 2005).
lung carcinoma (41 papers, 2003 to 2026). "There was also suggestive evidence for possible associations of IL-1β, IL-1Ra, IL-36γ with lung cancer, IL-1α/β, IL-1Ra with LUAD, and IL-1β, IL-18BP with LUSC, perhaps via other IL-1 family members/receptors." (PMID 34475499, 2021). "We found that both IL-1α and IL-1β were predictive of elevated risk for lung cancer risk." (PMID 39236155, 2024). "We then tested the probative value of the IL-1α mRNA program as a predictor of lung cancer risk." (PMID 39236155, 2024). "Our comprehensive MR study suggests that IL-1Racp might cause lung cancer, perhaps via IL-1α/β and IL-1Ra." (PMID 34475499, 2021). "However, suggestive total effects of increased risk were noted for genetically predicted IL-1Racp with lung cancer (P = 0.006), IL-1α with LUAD (P = 0.027), and IL-1Racp with LUSC (P = 0.008)." (PMID 34475499, 2021). "However, genetic instruments for IL-1Ra which is drugged by anakinra were associated with lung cancer/LUAD only after adjustment for the genetically predicted effects of IL-1α and IL-1β in this study." (PMID 34475499, 2021). "However, our group demonstrated that AIM2 inflammasome could play a pro-carcinogenic role in lung cancer, in that its activation in tumor-associated pDCs leads to high levels of IL-1α which favors lung tumor cell proliferation in a caspase-4-dependent manner." (PMID 34084280, 2021). "Since PNO1 knockdown inhibited the expression of PTGS2, a gene involved in inflammation, we sought to examine the effects of inhibiting PNO1 on the expression of inflammatory cytokines (IL‐1α and IL‐8) in lung cancer cells." (PMID 36625087, 2023). "By treating the lung cancer cells, A549, H460, and H1299, with CoCl2, the mRNA levels of IL1A and IL6 were mildly induced." (PMID 34362882, 2021). "We primarily assessed the effects of genetically predicted IL-1α, IL-1β, IL-1Ra, IL-1Racp, IL-18, and IL-18BP with lung cancer and its subtypes of LUAD and LUSC, because LUAD is more common than LUSC in people of European ancestry." (PMID 34475499, 2021). "Genetically predicted higher circulating IL-1Ra was suggestively positively associated with increased risk of both lung cancer and LUAD after adjusting for genetically predicted effects of IL-1α and IL-1β." (PMID 34475499, 2021). "Suggestive direct effects were also noted for IL-1β, IL-1Ra, IL-36γ with lung cancer, IL-1α/β, IL-1Ra with LUAD, and IL-1β, IL-18BP with LUSC, after adjusting for genetically predicted effects of other IL-1 family members/receptors." (PMID 34475499, 2021). "We found that high hypoxic stress in lung cancer is correlated with inflammatory cytokine secretion and expression in the tumor microenvironment, including IL1A and IL6." (PMID 34362882, 2021). "In contrast, healthy cells had a basal release of IL-1α at approximately 20 pg/ml, while the release from lung cancer cells was higher (~34 pg/ml), suggesting that even low (detectable) levels can be involved in lung pathogenesis." (PMID 28223692, 2017). "Tumor necrosis factor α and IL-1α were also reported to be released in H446 lung cancer cells after irradiation with γ-rays (8 Gy), but only TNF-α after irradiation with accelerated carbon ions (290 MeV/n, LET 13 keV/μm, 2 Gy)." (PMID 28638385, 2017). "We found that TAMs are another source of IL-1α and IL-1β release in lung cancer lesions in tumor-bearing mice." (PMID 27528423, 2016). "Interleukin-1 alpha was shown to enhance the adhesion of A549 lung carcinoma and M6 melanoma cells to the vascular surface both in vitro and in vivo, suggesting that IL-1 proteins facilitate the metastatic process." (PMID 12865923, 2003). "In vitro, TLR8 agonist stimulation of lung cancer cells resulted in the activation of NF‐κB, increased expression of proinflammatory factors (IL‐6, IL‐8, GM‐CSF, IL‐1α, and IL‐12), and increased expression of antiapoptotic proteins Bcl‐2, VEGFR2, and chemokine receptors." (PMID 39003635, 2024).
lung carcinoma (continued). "This adds additional randomized evidence showing that IL-1Racp may partially operate on lung cancer via especially IL-1α/β and IL-1Ra possibly by suppressing innate responses." (PMID 34475499, 2021). "Genetically predicted higher circulating IL-1β was inversely associated with LUAD and LUSC, and was suggestively associated with decreased lung cancer risk after adjusting for genetically predicted effects of IL-1α and IL-Ra, without pleiotropy identified." (PMID 34475499, 2021). "The effect of IL-1Racp in lung cancer may work via IL-1α/β and IL-1Ra by sharping the tumor microenvironment, leading to an suppressed immune responses." (PMID 34475499, 2021). "This first MR study comprehensively assessing the causal roles of IL-1 family members/receptors in lung cancer and its subtypes, provided suggestive evidence for associations of increased IL-1Racp with increased lung cancer/LUSC, and increased IL-1α with increased LUAD." (PMID 34475499, 2021). "Taken together, our findings suggest that interventions decreasing IL-1Racp might protect against lung cancer, perhaps via IL-1α/β or IL-1Ra." (PMID 34475499, 2021). "Besides, high expression of TIFA and IL1A as a gene, which regulates tumor growth, angiogenesis, and metastasis in lung carcinoma cell has been reported." (PMID 33765916, 2021). "Similarly to what observed in mice, caspase-4 was correlated to the stage of lung cancer in humans in that it induced cell proliferation in a K-Ras, c-MyC and IL-1α dependent manner." (PMID 33187551, 2020). "Moreover, in our previous study, we found that plasmacytoid dendritic cells (pDCs) derived from the cancerous lesions of patients with lung cancer were able to release IL-1α, rendering pDCs tolerogenic in that they highly populated tumour lesions, thus implying their role in tumour proliferation." (PMID 28223692, 2017). "Our data identified the steady-state decline in DNMT3A as a contributing factor to the enhanced production of IL-1α by monocytic cells, providing novel mechanistic evidence for the relationship between CHIP, inflammaging, and lung cancer." (PMID 39236155, 2024). "Subepithelial lung myofibroblasts (SELMs) isolated from tissue biopsies of patients undergoing surgery for lung cancer were stimulated with TNF-α (50 ng/mL), IL-1α (5 ng/mL), added alone or in combination, and TGF-β1 (5 ng/mL)." (PMID 37509671, 2023). "Similar with the bioinformatics results in TCGA database, our experiments confirmed the expression of CLEC7A, TLR7, IL-1A and IL33 were decreased in lung cancer." (PMID 37259066, 2023). "To further confirm the correlation between IL1A, IL6, and HIF1α, we analyzed the expression of these two genes in 16 patients with lung cancer." (PMID 34362882, 2021). "We examined expression of IL-1A, IL-1B, IL-6 and IL-8 in two pairs of gefitinib-sensitive (PC9, and HCC827) and gefitinib-resistant (PC9/gef, and HCC827/gef) lung cancer cell lines to identify the specific cytokine involved in gefitinib resistance by RT-qPCR." (PMID 25871388, 2015). "One previous study found that TAS was positively correlated with proinflammatory cytokines IL-1α, IL-6, and TNF-α in bronchoalveolar lavage fluid in lung cancer patients." (PMID 25254081, 2014). "IL-1α blockade delayed lung cancer progression more robustly than IL-1β blockade; notably, though, the combination of both exhibited an apparent synergistic effect in reducing tumor growth that was comparable to treating mice with anakinra." (PMID 39236155, 2024). "In contrast to IL-1β and IL-33, the precursor form of IL-1α and recombinant human mature IL-1α have the same biological activity in inducing IL-6 and TNF-α in human peripheral blood mononuclear cells (PBMCs) and lung cancer cells." (PMID 31795299, 2019).
lung carcinoma (continued). "Similarly, PBMCs from smokers, a population well known to be at high risk of lung cancer, released higher levels of IL-1α and IL-10 than PBMCs from non-smokers, implying that the release of both types of cytokines may favour cell transformation and thus carcinogenesis." (PMID 28223692, 2017). "In coculture, U937 macrophages have been shown to secrete TNF-α and IL-1α (IL-1α not at high doses) after irradiation of NCI-H446 lung cancer cells with γ-rays (137Cs Source, 8 Gy) but only TNF-α after irradiation with accelerated carbon ions (290 MeV/n, LET 13 keV/μm, 2 Gy)." (PMID 28638385, 2017). "To further refine this observation, we also tested whether IL-1α derived from stressed non-immune cells – given its prototypical function as an alarmin released by cell stress, damage, or senescence – contributes to the age-enhanced progression of lung cancer." (PMID 39236155, 2024). "In addition, we were not able to detect any increase in other inflammatory cytokines (e.g., IL-1α, IL-1β, IFN-α, IL-8 and IL-18) from both healthy and lung cancer-derived PBMCs after S1P stimulation (data not shown)." (PMID 36010601, 2022).